ENO1 (enolase 1)
Diseases named in the same sentence as ENO1 in open-access papers (continued):
Sharing a sentence is not in itself a finding about the gene and the disease.
lung cancer (77 papers, 2007 to 2026). A malignant neoplasm involving the lung. "IHC and Western blot analyses have shown that ENO1 protein is overexpressed in lung cancer tissues, and associated with increased tumour growth, migration, and invasion." (PMID 41154605, 2025). "In other types of tumors, high levels of FAP in tumors are associated with poor survival, and in lung cancer, ENO1 is a biomarker associated with patient survival." (PMID 34035230, 2021). "For instance, treatment of lung cancer cells with anti-ENO1 monoclonal antibodies in vitro suppressed cell-associated plasminogen and matrix metalloproteinase activation, collagen and gelatin degradation, and cell invasion." (PMID 33584813, 2020). "Enhanced expression of ENO1 has been implicated in human tumorigenesis and also used as a diagnostic marker for human lung cancer." (PMID 22014164, 2011). "Overexpression of ENO1 in breast, and lung cancers is associated with tumor progression and rapid tumor growth." (PMID 22110952, 2011). "Meanwhile, ENO1 has been implicated in the progression and metastasis of lung cancer." (PMID 41154605, 2025). "In this study, we aimed to assess the influence of tumor-associated ENO1 on anti-ENO1 immunity in lung cancer and investigate the relationship between levels of ENO1 Ag in lung cancer cells and levels of anti-ENO1 Ab in the plasma of lung cancer patients." (PMID 26551021, 2015). "The irregular expression of ENO1 has been linked to tumour progression in several cases of breast and lung cancer, and the ENO1 protein level in the plasma of non-small cell lung cancer patients was significantly higher than that in the plasma of healthy individuals." (PMID 24099319, 2013). "However, a recent report has demonstrated that ENO1 is the promising biomarker that may provide more diagnostic efficacy for lung cancer." (PMID 26185761, 2015). "Functional assays demonstrated that ENO1 silencing substantially impaired the invasive capacity of both lung cancer cell lines in Transwell assays." (PMID 41514669, 2026). "Our findings highlight the critical role of circFUT8 in lung cancer progression through its regulation of M2 macrophage polarization via interaction with ENO1." (PMID 41328768, 2025). "The interaction between circFUT8 and ENO1 represents a novel therapeutic target for lung cancer, and future research will further investigate the potential applications of circFUT8 in cancer therapy." (PMID 41328768, 2025). "Studies have shown that the PRMT-6PGD/ENO1 axis is critical for lung cancer progression, and inhibiting the signaling of this axis can enhance antitumor effect of cisplatin in preclinical lung cancer models." (PMID 40227333, 2025). "High ENO1 expression predicts poor prognosis in patients with liver cancer and lung cancer and also indicates more severe tumor type and later stage tumors (Zhang, Lu & Yang, 2020; Zhang, Wang & Dong, 2018)." (PMID 37810778, 2023). "In lung cancer, patients with overexpressed ENO1 tend to show poor clinical results, with shortened overall and progression-free survival." (PMID 35434271, 2022). "Vaccination of BALB/c mice with these inactivated transfectants after implantation of murine ENO1-positive lung cancer cells prevented the development of otherwise massive tumors in their peritoneal cavity." (PMID 35214706, 2022). "Conversely, a knockdown of ENO1 in pancreatic, breast, and lung cancer cell lines induced an inhibition of cell cycle and the cell senescence." (PMID 35204345, 2022). "The ENO1 can be expressed in the cytoplasm and cell membrane, and its overexpression is closely related to various tumors, such as lung cancer, oral cancer, and gastric cancer." (PMID 36361568, 2022). "The self-renewal, growth, and invasion capacity of CSCs can drive malignant transformation, thus ENO1-mediated enhancement of these aggressive phenotypes of LCSCs would promote the lung cancer progression." (PMID 33579362, 2021).
lung cancer (continued). "And in the study of glioma and lung cancer, ENO1 has been considered to be a possible promoter of tumor metabolism and make those tumor cells with high expression of ENO1 have growth advantage." (PMID 34035809, 2021). "A previous study of our group has found that ENO1 promotes lung cancer progression through activating PI3K/AKT signaling pathway." (PMID 34335983, 2021). "ENO1 was highly expressed in lung cancer tissues and promoted LUAD progression by regulating the glycolytic pathway." (PMID 34544452, 2021). "Overall, this finding supported that ENO1 was an oncogene in lung cancer and emphasized the importance of ENO1 on stem cell maintenance, implicating a potential target for the stem cell therapy of lung cancer." (PMID 33579362, 2021). "Studies had found that the expression of ENO1 was related to the proliferation, invasion, and migration of tumors, including lung cancer, gastric cancer, glioma, and pancreatic ductal glands cancer." (PMID 34504528, 2021). "Five of them showed that the expression of ENO1 was increased in lung cancer by immunohistochemistry and real-time fluorescence quantitative polymerase chain reaction (RT-qPCR)." (PMID 34504528, 2021). "ENO1 was highly expressed in the lung cancer cell line H1299 and stimulated the proliferation of tumor cells." (PMID 34504528, 2021). "A recent study reported that ENO1 promoted the self-renewal and malignant phenotype of lung cancer stem cells by affecting the AMPK/mTOR pathway." (PMID 34627260, 2021). "In six studies, the expression of ENO1 was observed to be upregulated or downregulated in lung cancer tissues, which suggested that the clinical influence of ENO1 in lung cancer tissues remained obscure." (PMID 34504528, 2021). "More importantly, we revealed that ENO1 plays an oncogenic role in lung cancer by facilitating self-renewal, growth, and invasion of LCSCs." (PMID 33579362, 2021). "The other study implies that serum ENO1 antibody levels are significantly higher in the lung cancer than those in the control or in the benign lung disease groups (P < 0.001)." (PMID 34671213, 2021). "Patients with lung cancer overexpressing ENO1 also showed poor clinical outcomes, with shorter overall and progression-free survival, compared to low expressing patients." (PMID 33584813, 2020). "Recently, It has been shown that ENO1 expression is abnormal in many human cancers, including glioma, colorectal cancer, pancreatic cancer, lung cancer, and head and neck cancers." (PMID 33067426, 2020). "Some ANXA5-regulated proteins such as FN1, ENO1, heat shock and Keratin family numbers are closely related to invasion and progression of lung cancer." (PMID 27684953, 2016). "Blocking surface-expressed ENO1 with anti-ENO1 Ab, or down-regulation of ENO1 expression by shRNA, significantly suppressed the invasiveness of lung cancer cells in vitro and reduced metastasis of lung cancer cells in vivo." (PMID 26551021, 2015). "We also evaluated the immunosuppressive activity of tumors on the levels of anti-ENO1 Ab, and the importance of anti-ENO1 Ab on the clinical outcomes of lung cancer patients." (PMID 26551021, 2015). "To investigate the impact of tumor mass on the immune status of lung cancer patients, we examined the level of anti-ENO1 Ab before and after surgery." (PMID 26551021, 2015). "ENO-1 was found to be significantly overexpressed in effusion-derived tumor cells and tumor specimens of lung cancer." (PMID 25407528, 2014). "In our previous studies, we observed that ENO1 was overexpressed in the tumor of non-small cell lung carcinoma patients and displayed on the surface of lung cancer cells." (PMID 23894455, 2013). "We next examined the effect of incubation with ENO1-specific Ab on the activation of plasmin in LLC/luc lung cancer cells." (PMID 23894455, 2013).
lung cancer (continued). "Moreover, by binding to 2-PG (2-phosphoglycerate) and regulating the pentose phosphate pathway (PPP), ENO1 can significantly increase tumorigenicity and platinum resistance in lung cancer." (PMID 40303285, 2025). "The methylation of ENO1 caused by arginine methyltransferase 6 facilitates the generation of active ENO1 dimers and its binding affinity to 2-PGA, resulting in increased tumor growth and cisplatin tolerance in lung cancer." (PMID 40612109, 2025). "Alpha-enolase (ENO1) were previously reported to promote metastasis of lung cancer via HGDR and Wnt signaling pathway and higher anti-ENO1 antibody level was associated with better progression-free survival in non-small cell lung carcinoma (NSCLC) patients after surgery." (PMID 38182978, 2024). "Similarly, ENO1 can reportedly promote lung cancer metastasis via the HGFR and WNT signaling pathways." (PMID 37391802, 2023). "Moreover, ENO1 was identified to promote the self-renewal and malignant phenotype of lung cancer stem cells by AMPK/mTOR pathway, and MPK/mTOR pathway is also the upstream initiator during the onset of autophagy mechanism." (PMID 35130884, 2022). "ENO1 promotes lung cancer metastasis via HGFR and WNT signaling." (PMID 36620599, 2022). "Additionally, ENO1 is commonly overexpressed in different tumor types, including melanoma, pancreatic, breast, and lung cancer, thus citrullinated ENO1 peptides are plausible antigens for a wide cancer spectrum." (PMID 36291752, 2022). "Previous studies have found that PhAH was a pan-enolase inhibitor, which could effectively inhibit the activity of ENO1, thereby suppressing the growth of pancreatic, breast, and lung cancers." (PMID 35836227, 2022). "Similarly, a citrullinated ENO1 peptide-based vaccine elicited a potent citrulline-specific Th1 cell response in pancreatic, skin, and lung cancers." (PMID 36291752, 2022). "Thus, the ENO1-mediated activation of mTOR pathway would contribute to the stem cell maintenance of lung cancer." (PMID 33579362, 2021). "However, results from other six research reports varied in the expression of ENO1 in lung cancer tissues, and these studies had their limitations." (PMID 34504528, 2021). "ENO1 might also contribute to the progression of lung cancers by stimulating cell proliferation via accelerating G1/S transition, but not in esophageal cancers." (PMID 33643901, 2020). "ENO1 has been suggested as a biomarker candidate for lung cancer." (PMID 27684953, 2016). "This link implies a functional relationship and suggests the important role of ENO1 in lung cancer." (PMID 26185761, 2015). "Our results suggest that the increase of anti-ENO1 Ab may reflect anti-tumor immune responses and serve as a prognostic marker in postoperative lung cancer patients." (PMID 26551021, 2015). "Furthermore, ENO1 was identified as a tumor antigen in lung cancer with different proteomic methods by two independent scientific groups." (PMID 23914992, 2013). "The elevated levels of ENO1 protein in the tumor tissues and the plasma samples from NSCLC patients indicate ENO1 may be a candidate biomarker of lung cancer." (PMID 21159241, 2010). "Subsequently, we found that the 43–55 kDa protein band purified from lung cancer sphere cells has a sequence coverage of 34% with human ENO1 and exists an interaction with 12C7 by immunoprecipitation, which was consistent with the result of commercial antibody to ENO1." (PMID 33579362, 2021). "Besides, anti-ENO1 mAb could attenuate lung cancer cell proliferation, invasion, and metastasis by inhibiting ENO1-mediated GSK3β activation and inactivating the Wnt pathway, and MET might restrain the survival of cancer cells, the stemness of CSCs and EMT by inactivating the Wnt/β-catenin pathway." (PMID 38515460, 2024). "The regulation of ENO1 directly activates HGF-MET signaling and Wnt-LRP5/6, in a manner indirectly driven by an EMT phenotype in studied lung cancer models." (PMID 37381723, 2023).
lung cancer (continued). "We also tested it in lung cancer and experiment results confirmed the interaction between CCDC65 and ENO1 and the overexpression of CCDC65 promoted the ubiquitination of ENO1." (PMID 35844805, 2022). "The improvement of cell survival by ENO1 was by upregulating p38 in the MAPK cascade and increasing p-AKT in the AKT cascade, in particular in lung cancer cell lines." (PMID 35434271, 2022). "Recent studies have found that ENO1 participates in the EMT-regulating process, tumor infiltration, and metastasis in malignant epithelial tissues in lung cancer, gastric cancer, and endometrial cancer." (PMID 35434271, 2022). "Previous studies have reported that NDUFA4 promotes the progression of lung cancer cells via activating PI3K/AKT pathway and the PI3K/AKT pathway is responsible for glycolysis by regulating HIF-1α target genes ENO1 and LDHA." (PMID 35977935, 2022). "For example, Enolase 1 (ENO1) is a glycolysis enzyme which performs crucial roles in glucose metabolism and contributes to progression of lung cancer." (PMID 33634138, 2021). "It is worth noting that, among these identified proteins, five proteins (Hsp90, ENO1, ALDOA, PDIA6, HSPA5) were reported as the differential proteins identified in lung cancer tissues as compared to normal lung in our previous work." (PMID 27684953, 2016). "This SCG label-free lung cancer biosensor showed to have the lower detection limits ever reported for the three different tumors markers ANXA2, VEGF, and ENO1." (PMID 26805845, 2016). "After the immobilization process of the antibodies, the label-free suspended SCG sensor was ready for detection of the important lung cancer biomarkers: ANXA2, VEGF, and ENO1." (PMID 26805845, 2016). "In our animal experiments, we employed a murine lung cancer cell line, LLC, and a murine hepatoma cell line, ML-1, both expressing substantial amounts of ENO1 on the surface." (PMID 26551021, 2015). "The same group further demonstrates that blockage of cell surface-bound ENO-1 reduces PLA-dependent ECM breakdown and thus cell invasion resulting in diminished metastatic potential of lung cancer cells in vivo." (PMID 25407528, 2014). "Nevertheless, a recently published study shows the presence of ENO-1 at the sites of pericellular ECM degradation and its co-localization with uPAR and PLG on lung cancer cells." (PMID 25407528, 2014). "The expressions of ENO1, uPA, uPAR and plasminogen on the surface of PE089 cells, a human lung cancer cell line, and the murine Lewis lung carcinoma cells transfected with the luciferase gene (LLC/luc) were examined and confirmed by FACS analysis." (PMID 23894455, 2013). "In this study, we demonstrated that surface ENO1 interacted with plasminogen, uPA and uPAR on the PE089 and LLC/luc lung cancer cell lines." (PMID 23894455, 2013). "Furthermore, a comparative proteomics analysis revealed that MUC5B, IQGAP, ENO1 and SPARCL1 were identified in the salivary exosomes of lung cancer patients." (PMID 40575159, 2025). "Besides being the marker of exosomes, ALDOA, ENO1 and YWHAG can promote metastasis, invasion, activation and proliferation of lung cancer." (PMID 36387251, 2022). "In summary, our study was the first to reveal the circRNA-regulated glycolysis in LUAD, disclosing that circRNA-ENO1 promoted proliferation and EMT in LUAD through upregulating its host gene ENO1, providing circ-ENO1 as a new potential biological marker in lung cancer." (PMID 31767835, 2019). "Interestingly, in our previous report, we demonstrated that PRMT6 asymmetrically dimethylates the R9 and R372 sites of ENO1 in lung cancer, which is different from our finding in this study that PRMT5 only symmetrically dimethylates the R9 site of ENO1 in ovarian cancer." (PMID 36999124, 2023).
lung cancer (continued). "While adoptive transfer of Ab against ENO1 was observed to suppress the establishment of lung metastasis by lung cancer cells, the prolonged treatment of ENO1-specific Ab at the later stage of metastasis did not significantly improve the therapeutic effect (experiments 1 and 2 in Figures 5Dand8D)." (PMID 23894455, 2013). "Additionally, protein arginine methyltransferase 6 (PRMT6) mediated methylation at R9 and R372 of ENO1 promotes the formation of its active form and facilitates the binding of 2-phospho-glycerate to ENO1, thereby upregulating glycolysis and DDP resistance in lung cancer." (PMID 40264038, 2025). "Indeed, in this study we demonstrated that blocking ENO1 by treatment with an ENO1-specific Ab or suppressing ENO1 expression by treatment with a specific shRNA plasmid reduces plasmin and MMP2/9 activation, ECM degradation, and invasion capacity in lung cancer cells." (PMID 23894455, 2013). "However, the co-lethality paradigm applies specifically to pancreatic cancer cells, as simultaneous inhibition of ENO1 and GLS did not synergize in inhibiting MDA-MB-231 or NCI-H441 breast and lung cancer cell survival." (PMID 26734996, 2016).